IL21 (interleukin 21)
Diseases named in the same sentence as IL21 in open-access papers (continued):
Sharing a sentence is not in itself a finding about the gene and the disease.
periodontitis (18 papers, 2016 to 2026). An acute or chronic inflammatory process that affects the tissues that surround and support the teeth. "Similarly recent studies have associated Interleukin-21 levels with periodontitis." (PMID 26998377, 2016). "Levels of Th17-related cytokines, such as IL-17, IL-23 and IL-21 were found upregulated in gingival tissues of periodontitis patients, and the levels of these proinflammatory cytokines were shown to be correlated with the severity of alveolar bone destruction." (PMID 40933993, 2025). "IL-21 in particular appears to be a promising biomarker for differentiating between gingivitis and periodontitis." (PMID 36013509, 2022). "A statistically significant difference in the mean concentrations of IL-21 was observed between Groups B (chronic gingivitis) and C (chronic periodontitis)." (PMID 36013509, 2022). "The IBD activity was associated with significantly increased expression of IL-4, IL-10 and IL-21 in the gingival tissue of patients with periodontitis." (PMID 34501547, 2021). "Previously reported overexpression of Th17 cytokines (IL-17, IL-21, and IL-23) in chronic periodontitis patients in Brazilian and Chilean population have been well documented and indicates that Th17 facilitates the progression of inflammation." (PMID 34104811, 2021). "Increased IL-21 in periodontitis explains its synergistic destructive capability with cocontributing factors, whereas its presence in healthy tissue reveals its protective role." (PMID 34104811, 2021). "Although periodontitis pathophysiology involves complex interplay between pro-and anti-inflammatory signaling, data on IL-21 revealed elevated levels in both GCP and GAP." (PMID 34104811, 2021). "In our study, we demonstrated that ligature-induced periodontitis can upregulate the levels of inflammatory factors, especially IL-6 and IL-21." (PMID 33757547, 2021). "Recently, a systematic review reported elevated IL-21 levels in chronic periodontitis patients compared to healthy controls." (PMID 34104811, 2021). "Several studies in addition to our data reveal a positive correlation of IL-21 to clinical periodontal parameters, thereby strengthening evidence of its role in periodontitis pathophysiology." (PMID 34104811, 2021). "When a research group extracted B cells and conditioned them ex vivo using a mixture of anti-Tim1, CD40L, and IL-21, then transferred them to mice models of periodontitis, they observed an improvement of bone injury and resorption." (PMID 32604936, 2020). "Previous studies in humans have shown that elevated levels of some cytokines, such as IL-1β, IL-6, IL-21, and IL-23, are necessary for promoting Th17 differentiation and maintenance during the destructive phase of periodontitis." (PMID 28497028, 2017). "Future longitudinal studies are required to prove the definitive role of IL-21 in periodontitis and compare IL-21 levels among types of periodontitis." (PMID 26998377, 2016). "As CAL is the most reliable indicator of periodontal tissue destruction, this correlation indicates better that IL-21 levels increase with the severity of periodontitis." (PMID 26998377, 2016). "This indicated the role of IL-21 in Ig-isotype switching in chronic periodontitis and its influence on the adaptive immune response and the immunomodulation of oral mucosa under the challenge of periodontal pathogens." (PMID 26998377, 2016). "Gingival tissue IL-21 (3.35 pg/mL) and GCF IL-21 (8/10) were higher in CP (chronic periodontitis) compared to controls." (PMID 26998377, 2016). "All methodologies showed increased IL-21 levels in periodontitis, among which ELISA showed maximum detection of IL-21." (PMID 26998377, 2016). "This systematic review included cross-sectional studies (level III) and thus indicates a low level of evidence to prove the definitive role of IL-21 in periodontitis." (PMID 26998377, 2016). "Salivary levels of IgA were increased in periodontitis subjects along with gingival levels of IL-21." (PMID 26998377, 2016).
periodontitis (continued). "All the samples showed increased IL-21 levels in periodontitis, among which GCF showed maximum detection of IL-21 (80.336 pg/mL)." (PMID 26998377, 2016). "In the paper that compared cytokine levels for 54 periodontitis patients and 40 healthy controls, cytokines IL‐1β, IL‐4, IL‐6, IL‐10, IL‐17A, IL‐17F, IL‐21, IL‐22, IL‐23, IL‐25, IL‐31, IL‐33, IFN‐γ, sCD40L and TNF‐α were measured in saliva and serum at baseline, 3, 6 and 12 months after treatment." (PMID 41580300, 2026). "We also observed that six molecules (IL-4, IL-5, IL-12, IL-13, IL-21, and IL-23) were intimately related in the periodontitis sites of all evaluated groups, regardless of risk factors." (PMID 37835794, 2023). "In particular, IL-21 appears to be a promising biomarker for differentiating between gingivitis and periodontitis, and is worthy of further well-structured randomized controlled trial-based research to develop it as a discriminatory marker for the early detection of periodontal disease conditions." (PMID 36013509, 2022). "In some experiments, the level of IL-21 in the serum and saliva of patients with chronic periodontitis significantly increased, and the level of IL-21 is down-regulated after periodontal treatment, suggesting that IL-21 may promote periodontitis." (PMID 34557201, 2021). "Although further longitudinal studies are necessary, IL-21 may serve as a potential inflammatory biomarker in screening for generalized chronic and aggressive periodontitis." (PMID 34104811, 2021). "More experiments are needed to examine whether IL-21 is the driver/inhibitor/bystander of periodontitis." (PMID 34557201, 2021). "One study showed reduced expression of salivary IL-21 in periodontitis using ELISA." (PMID 26998377, 2016). "In this regard, this systematic review aimed to evaluate the expression of IL-21 in periodontitis." (PMID 26998377, 2016). "All cross-sectional studies showed increased expression of IL-21 in periodontitis." (PMID 26998377, 2016). "Further research in the field of Interleukin-21 could throw light on a better understanding of its role in the pathogenesis of tissue destruction in periodontitis." (PMID 26998377, 2016). "Data from such studies may support and strengthen evidence to classify IL-21 as a biomarker in periodontitis and would clarify its role in the balance between Tregs, Th17 cells, Th2 cells, and their crosstalk in the pathophysiology associated with tissue inflammatory destruction." (PMID 34104811, 2021). "Several pro-inflammatory cytokines, including IL-1, IL-6, IL-12, IL-17, IL-18, IL-21, TNF-α, and IFN-γ, play a critical role in the pathogenesis of periodontitis." (PMID 40136726, 2025). "Regarding intestinal tissue analyses, higher levels of IL-1β, IL-4, IL-6, IL-17A, IL17F, IL-21, IL-31, IL-33 and soluble CD40 ligand (sCD40L) were found in patients having IBD activity and periodontitis." (PMID 34501547, 2021). "In patients with periodontitis, the present study observed increased levels of pro-inflammatory factors IFN-γ, IL-1β, IL-2, IL-7, IL-21, and TNF-α, in addition to decreased levels of anti-inflammatory factors IL-5 in GCF of T2DM patients." (PMID 33417619, 2021). "Regarding intestinal tissue analyses, higher levels of IL-1β, IL-4, IL-6, IL-17A, IL17F, IL-21, IL-31, IL-33 and sCD40L were found in patients with IBD and periodontitis." (PMID 34501547, 2021). "The aim of this study was to compare IL-21 levels in gingival crevicular fluid among patients with generalized chronic periodontitis (GCP), aggressive periodontitis, and healthy gingiva (HG) and to correlate IL-21 levels with clinical parameters." (PMID 34104811, 2021). "Thus, the aim of this study was to compare IL-21 levels in GCF among patients with generalized chronic periodontitis (GCP), aggressive periodontitis, and healthy gingiva (HG) and to correlate IL-21 levels with clinical parameters." (PMID 34104811, 2021).
periodontitis (continued). "The systematic review included cross-sectional studies quantifying IL-21 in GCF, saliva, and gingival tissues along with a study reporting reduction in IL-21 levels in chronic periodontitis following non-surgical periodontal therapy." (PMID 34104811, 2021). "As found in the present study, in T2DM patients with periodontitis, statins treatment reduced pro-inflammatory factors IFN-γ, IL-1β, IL-2, IL-6, IL-7, IL-21 and TNF-α levels in GCF, and enhanced anti-inflammatory factors IL-4 and IL-5 levels through the anti-inflammation and anti-oxidation effects." (PMID 33417619, 2021). "In patients with periodontitis, lower levels of pro-inflammatory factors IFN-γ, IL-1β, IL-2, IL-6, IL-7, IL-21, TNF-αand higher levels of anti-inflammatory factors IL-4 and IL-5 in gingival crevicular fluid in the Sp group were identified than those in the Dp group." (PMID 33417619, 2021). "Indirectly, these cells can also induce the amplification of the pro-inflammatory cytokines (IL-1, IL-6, IL-12, IL-17, IL-18, IL-21, TNF-α, and IFN-γ), which are known to be found in periodontitis and to induce osteoclastogenesis via the RANKL–RANK–OPG pathway." (PMID 33143068, 2020). "The results of this systematic review show that five out of six studies show an increase in IL-21 levels in chronic periodontitis subjects and one study showed no increase in periodontitis." (PMID 26998377, 2016). "While all the cross-sectional studies showed elevated IL-21 levels in periodontitis, one recent study showed contradictory results by reporting no significant domination of Th17 cytokines in chronic periodontitis." (PMID 26998377, 2016). "However, there are no studies in the literature quantifying GCF IL-21 levels from aggressive periodontitis or studies comparing the GCF levels of IL-21 in aggressive and chronic periodontitis." (PMID 34104811, 2021). "There are no studies based on comparison of IL-21 levels among types of periodontitis." (PMID 26998377, 2016).
Allergy (17 papers, 2011 to 2025). An allergy is an immune response or reaction to substances that are usually not harmful. "Expression of allergy-associated cytokine genes, including Il4, Il5, Il9, Il13, and Il21, was higher in Nr4a-TKO cells, even when compared with Foxp3-KO cells." (PMID 33665581, 2021). "It is well known that Th2 cells primarily contribute to the development of parasitic infections and allergic diseases, in which IL-21 plays a dual role." (PMID 40376002, 2025). "TFH cell subsets and functional molecules (primarily IL-4 and IL-21) play critical roles in the occurrence, progression, and maintenance of allergic diseases." (PMID 39822282, 2025). "While higher BAFF concentrations at birth are negatively associated with the development of allergic disease, the association of BAFF, APRIL, and IL-21 concentrations with vaccine responses is a novel finding from our study." (PMID 37251388, 2023). "A subpopulation of Th17 lymphocytes mainly produces the cytokines IL-17, IL-21 and IL-22, regulates inflammatory processes and participates in the response directed against microorganisms and in the development of allergic diseases." (PMID 36139446, 2022). "Regarding the role of IL-21 in allergies, there have been conflicting effects on eosinophil cells." (PMID 36032502, 2022).
celiac disease (17 papers, 2008 to 2025). An autoimmune genetic disorder with an unknown pattern of inheritance that primarily affects the digestive tract. "Interleukin-21 has been linked to an increased disease risk, and the serum levels of IL-21 appear higher in celiac disease compared to healthy subjects and seem to correlate with serum anti-ttg antibodies and mucosal damage." (PMID 40547012, 2025). "Enhanced expression of IL-21 and/or IL-21R has been documented in various diseases including CD, UC, and celiac disease." (PMID 29849593, 2018). "The upregulation of T cell-secreted IL-21 has in particular been described in patients with CD and celiac disease." (PMID 29849593, 2018). "Forty eight of our DE genes belong to this pathway, including 4 genes that have been genetically linked to coeliac disease: CCR1, IL18RAP, IL21 and IL2RA." (PMID 26444573, 2015). "We found, as in celiac disease, strong upregulation of IL-17 signaling and Th17 cell differentiation in EED including induction of IL21, IL6, IL17A IL17F, IL22, IFNG, IL21R, and IL2RA." (PMID 39300663, 2024). "As regards coeliac disease diagnosis above 7 years of age in the case–control analysis, rs653178 (at SH2B3/ATXN2), rs13010713 (at ITGA4/UBE2E3), rs13151961 (at IL2/IL21), rs11712165 (at CD80) and rs10936599 (at MYNN) showed an association." (PMID 33446885, 2021).
pemphigus (17 papers, 2016 to 2024). Pemphigus is a group of rare autoimmune diseases that cause blistering of the skin and mucous membranes (mouth, nose, throat, eyes, and genitals).This conditioncan occur at any age, but often strikes people in middle or older age. "Moreover, upregulation of IL-21 and IL-17 were seen to associate with antigen-specific activation, therefore lend themselves as potential therapeutic targets in pemphigus." (PMID 36203615, 2022). "All this evidence led to suggesting a possible pathogenic role of IL-21 in pemphigus." (PMID 33954018, 2021). "IL-21 is a cytokine secreted mainly by Tfh and Th17 cells and has been suggested to stimulate B-cell activation and differentiation, leading to pathogenic autoantibody production in pemphigus lesions." (PMID 34660634, 2021). "The properties of IL-21 suggest its involvement in various immune system disorders, including pemphigus." (PMID 38107713, 2023). "In vitro culture of lymphocytes isolated from pemphigus skin lesions resulted in anti‐Dsg3 antibody production, significantly decreased by Trm depletion or IL‐21 blockade in the culture system." (PMID 36539957, 2023). "It is thus intriguing that the increase of Flavonifractor and positive correlation between Flavonifractor and circulating inflammatory markers (C5a, IL-6, IL-8, IL-7, IL-1β and IL-21) were reported in pemphigus vulgaris, a subgroup of pemphigus." (PMID 38022583, 2023). "Except for that, the latest research implicates that not only IL-4, but also IL-17 and IL-21 are closely correlated to the onset of autoimmune disorders like pemphigus." (PMID 35887732, 2022). "For example, we have reported the presence of both IL-21 and IL-17 in pemphigus lesions, which were secreted by infiltrated CD4+ T follicular helper- (Tfh-) like cells in our previous study." (PMID 34531933, 2021). "TNF-α, IL-6, IFNs, IL-17, IL-21, and IL-23 among others are known for their contribution to inflammatory process also in the course of pemphigus." (PMID 32170648, 2020). "By stimulating PBMC from pemphigus patients and controls with Dsg3 protein ex vivo, authors identified autoreactive IL-21-secreting cells in 50% of the pemphigus patients." (PMID 30065726, 2018). "In this study, pemphigus and MG patients showed elevated plasma concentrations of IL-21, a cytokine which is essential for B cell differentiation into class-switched plasma cells." (PMID 26872212, 2016). "As we found significantly elevated plasma concentrations of IL-21 (p = 0.01) in pemphigus patients we aimed to further track down the cellular source of IL-21." (PMID 26872212, 2016). "The further characterization of IL-21-producing T cells and of the role of IL-27 will lead to a more defined understanding of the auto-ab response in pemphigus." (PMID 26872212, 2016). "Most likely, these cells represent a population of IL-21-positive Tfh cells although in our pemphigus cohort the median percentage of IL-21 single positive T cells is lower compared to the median frequency of CD4+CXCR5+ T cells (16.91% CD4+ T cells)." (PMID 26872212, 2016). "In this context we conclude from our present results that IL-21 in pemphigus is partially released by activated Th17 cells since we detected IL-17/IL-21 double positive T cells in our patients and additionally IL-21 has been shown to promote the differentiation of Th17, as an autocrine factor." (PMID 26872212, 2016). "Moreover, we identified Dsg3-specific IL-21-producing cells in a significantly higher number in the analyzed pemphigus patients compared to HC by ELISpot assay." (PMID 26872212, 2016). "However, IL-21-producing Th17 cells only display a minor T cell population in the investigated pemphigus patients (0.11% CD4+ T cells) with IL-21 single positive T cells being more frequent (2.36% CD4+ T cells)." (PMID 26872212, 2016). "After stimulation with Dsg3 we could identify autoreactive IL-21-secreting cells in 50% of the pemphigus patients." (PMID 26872212, 2016).
pemphigus (continued). "However, a few pemphigus patients used for analysis of cTfh cells and IL-21 plasma levels were under systemic treatment." (PMID 26872212, 2016). "Next, we were interested whether Dsg3-specific IL-21-secreting T cells would contribute to the observed elevated IL-21 plasma levels in pemphigus." (PMID 26872212, 2016). "Circulating (c)Tfh cells (defined as CD4+CXCR5+ T cells) and Th17 cells (IL-17-producing CD4+ T cells) were significantly increased in pemphigus along with increasing IL-21 plasma concentrations suggesting an enhanced activation of IL-21-producing T cells in pemphigus." (PMID 26872212, 2016). "Therefore we stimulated PBMC from pemphigus patients and HC with Dsg3 protein ex vivo and analyzed the number of IL-21-secreting cells by ELISpot assay." (PMID 26872212, 2016). "T helper (Th) 17 cells were augmented in both pemphigus and MG patients while T follicular helper (Tfh) cells, which are essential in providing B cell help, were increased only in pemphigus along with increasing plasma concentrations of IL-21, a cytokine produced by Th17 and Tfh cells." (PMID 26872212, 2016). "As cTfh cells were increased in pemphigus we analyzed IL-21 production in pemphigus patients." (PMID 26872212, 2016). "Thus, antagonizing IL-27 and IL-21-production may represent a novel therapeutic option in pemphigus." (PMID 26872212, 2016). "One systematic review of cytokine research in pemphigus revealed elevated levels of TNF-α, TGF-β, interleukin (IL)-8, IL-10, IL-12, IL-17, and IL-21, along with reduced levels of IL-2 and IL-23." (PMID 39463588, 2024). "The pathogenesis of pemphigus involves a complex interaction among TH2, TH17, and TFH17 cells, with significant roles played by IL-4, IL-17, and IL-21." (PMID 39203983, 2024). "Although IL-4 production has been noted following COVID-19 vaccination, there is a lack of data regarding the levels of IL-17 and IL-21 in individuals who develop pemphigus post-vaccination." (PMID 39203983, 2024). "Pemphigus is a TH2 cell-driven disease, a complex TH17/TFH17 cell–dominated disease, and these cells produce lineage-specific cytokines like IL-4, IL-5, IL-17, and IL-21, and desmoglein-specific antibodies." (PMID 37496035, 2023). "Of note, IL-21 single positive CD4+ T cells tended to be increased in pemphigus and could be found more frequently (median: 2.36% CD4+ T cells) compared to IL-17/IL-21 double positive CD4+ T cells (median: 0.11% CD4+ T cells) in pemphigus patients." (PMID 26872212, 2016). "So far, to our knowledge elevated IL-21 levels have not been described in pemphigus, yet." (PMID 26872212, 2016).